EGFR (epidermal growth factor receptor)
Diseases named in the same sentence as EGFR in open-access papers (continued):
Sharing a sentence is not in itself a finding about the gene and the disease.
lung cancer (continued). "Other studies suggest that crosstalk between EGFR and Wnt may enhance lung cancer tumorigenesis." (PMID 26301867, 2015). "Treatment of lung cancer has moved towards individualized treatment using the combined assessment of immunohistochemical markers, mutational analyses, and FISH techniques in order to assess the exact histology and to detect, for example, KRAS and EGFR mutations or ALK translocations." (PMID 25968475, 2015). "Hence, EGFR-TKIs highly selective to mutated EGFR, but not to wild-type EGFR, can efficiently inhibit mutated EGFR in lung cancer cells without affecting the wild type EGFR expressed in epithelial cells." (PMID 26515464, 2015). "Furthermore, 17-DMAG reduces the growth of lung cancer cells with mutant EGFR, irrespective of the presence of a T790M mutation in mice xenograft models." (PMID 25780909, 2015). "Therefore, we asked whether C/EBPβ activity can be regulated by the EGFR signaling pathway in the lung cancer cells." (PMID 25767874, 2015). "miRNA profiling of lung cancer cell lines and lung tissues has demonstrated that miRNAs are emerging as unique effectors of the EGFR signaling pathway in lung cancer, in which miRNAs are correlated with the expression of EGFR and/or the EGFR mutant status or signaling activities." (PMID 26273639, 2015). "Thus, patients with EGFR-mutant lung cancer may benefit from high-dose treatment with EGFR inhibitors at reasonable toxicity." (PMID 26540572, 2015). "Therefore, our study may have relevant therapeutic implications for lung cancer patients, suggesting an effective strategy to overcome EGFR drug resistance." (PMID 26325669, 2015). "Furthermore, there is evidence for crosstalk between integrin and EGFR signaling in both breast and lung cancer, suggesting that successful targeting of these pathways in preM ER+ breast cancer may require a multi-pronged approach." (PMID 26251034, 2015). "In addition, in lung cancer cells, EGFR down-regulated miR-145 expression through ERK1/2." (PMID 26287249, 2015). "In our present study, we discovered a compound,referred to as 244-MPT, which could suppress either gefitinib-sensitive or -resistant lung cancer cell growth and colony formation, and also suppressed the kinase activity of both wildtype and double mutant (L858R/T790M) EGFR." (PMID 26517520, 2015). "Similarly, it is likely that the genetic background of EGFR-activated lung cancer cells may also modulate the extent of erlotinib sensitivity in EGFR-WT cells." (PMID 26247735, 2015). "Lung cancers arising in never smokers are suggested to have different molecular carcinogenic pathways and distinct profiles of oncogenic mutations; for example, lung cancer patients in never smokers are much more likely to carry mutations of epidermal growth factor receptor (EGFR)." (PMID 26020272, 2015). "For instances, miR-147 was downregulated in NSCLC, and overexpression of miR-147 could induce the MET of lung cancer cells, sequentially resensitize the resistance to EGFR-TKIs by inhibiting the Akt signaling pathway, and the MET phenotype of lung cancer cells could be attenuated by TGF-β." (PMID 26273639, 2015). "MiR-7 is a well-established regulator of EGFR, however it was also shown that miR-7 might be regulated by EGFR signaling: EGFR activation in lung cancer cells can stimulate miR-7 expression in an ERK-dependent manner, suggesting that EGFR induces miR-7 expression via the RAS-ERK pathway." (PMID 26287249, 2015). "Interestingly, in line with recent results showing the involvement of NF-κB signaling in modulating lung cancer dependence upon EGFR oncogenic signaling, 17 of the modulated kinases could directly or indirectly be linked to NF-κB pathway." (PMID 26015408, 2015). "Specifically, this new model uses detailed pharmacokinetic data to examine three possible clinical scenarios involving EGFR mutant lung cancer treated with erlotinib: mutation rates are independent of treatment, increase with treatment, or decrease with treatment." (PMID 26536620, 2015).
lung cancer (continued). "Furthermore, one study detailed a mechanism for such MET-mediated resistance by showing that an EGFR TKI-sensitive lung cancer cell line can develop resistance to gefitinib as a result of MET amplification via human epidermal growth factor receptor 3 (HER3)-dependent activation of PI3K." (PMID 25962919, 2015). "Finally, we note that the lung slice system could be utilized for studying the effects of other oncogenes known to be important in lung cancer such as mutated KRAS and EGFR and may also find application in the in vitro evaluation of cancer therapeutics." (PMID 25889156, 2015). "The dramatic responsiveness of EGFR-mutated NSCLC to small moleculeinhibitors of the EGFR kinase has provided a paradigm for the targeted therapy ofepithelial cancers and has established a new standard of care for a genetically definedsubset of patients with lung cancer." (PMID 25686219, 2015). "Furthermore, to confirm that the sensitivity/resistance profile data from Ba/F3 stable cells are also observed in EGFR mutated human lung cancer derived cell lines, we performed MTS assay with or without EGFR-TKIs using human lung cancer derived cell lines." (PMID 26515464, 2015). "Thus, patients with EGFR-mutant lung cancer may derive further benefit from such intermittent high-dose schedule." (PMID 26540572, 2015). "We then tested whether DAPT affected EGFR protein levels in lung cancer cells." (PMID 26497899, 2015). "In addition, a downregulation of miR-146a was reported in lung cancers, overexpression of miR-146a was found to suppress cell growth and migration, induce cellular apoptosis, and inhibit the EGFR downstream signaling components in lung cancer cell lines H358, H1650, H1975, HCC827, and H292." (PMID 26273639, 2015). "Among the nine variant-positive cases in the KRAS experiment, eight were EGFR mutation-negative lung cancers that had substitutions in codon 12, and one was an EGFR mutation-positive case in which the substitutions were non-synonymous and located outside of the hotspot region." (PMID 26126624, 2015). "Therefore, a strategy by targeting G protein-coupled receptor or c-MET may reverse lung cancer cells to EGFR-TKI resistance." (PMID 26273639, 2015). "Thus, EGFRTyr1068 was associated with lung cancer cells and tumors bearing EGFR-sensitizing mutations or with lung cancer cells and LCSCs that were sensitive to erlotinib treatment despite lack of EGFR mutation." (PMID 26247735, 2015). "In this study, we aimed to determine whether an inhibitory phenotype can account for the mutual exclusivity of KRAS and EGFR mutations in LUAD and to characterize the specific cellular effects that result from co-expression of both mutant alleles in lung cancer cells." (PMID 26047463, 2015). "However, for EGFR T790M mutated lung cancer, it failed to overcome EGFR T790M-mediated resistance in patients." (PMID 26515464, 2015). "However, no studies have directly addressed the role of the EGFR-L858R mutation in lung cancer cell invasion and MPE formation." (PMID 26338423, 2015). "Indeed, the reported frequency of baseline EGFR p.T790M mutations varies widely in the literature, ranging from 1% of all EGFR-mutant lung cancers to 35% of all EGFR-mutant lung cancers and depends of the sensitivity of the assays used and their ability to identify minor clones within a tumor." (PMID 24885034, 2014). "Therefore, we hypothesized that changed expression of genes related to EGFR endocytosis might be concerned with the different response of gefitinib treatment in lung cancer with wtEGFR." (PMID 24658031, 2014). "However, S2RPGRMC1 is enriched in endosomes in lung cancer cells, and the decreased endocytosis of mutant EGFR may limit the access of the two receptors to each other." (PMID 25594057, 2014). "Also, certain bone cancers might respond to treatment with erlotinib, an EGFR inhibitor that has been approved for use in lung cancers." (PMID 25029196, 2014).
lung cancer (continued). "One of the major findings of our study is that targeting HER-2 with Trastuzumab-DM1, an antibody-drug conjugate developed to improve the treatment of HER-2 positive breast cancer, may offer a new therapeutic approach in lung cancers expressing HER-2 even when resistant to EGFR TKIs." (PMID 24898067, 2014). "Therefore, the observation that wild-type EGFR lung cancers can be manipulated to render them sensitive to killing by dasatinib could have important implications for devising innovative and potentially more efficacious treatment strategies for this disease." (PMID 25501935, 2014). "Thus, EGFR endocytosis might be a potent mechanism which contributes to the therapeutic limitation of gefitinib in gefitinib-insensitive lung cancer with wtEGFR." (PMID 24658031, 2014). "Nevertheless, 10 ~ 20% patients with lung cancer without EGFR mutations therapeutically benefit from gefitinib, implying that EGFR mutations may not be the sole determinants of gefitinib efficacy." (PMID 24658031, 2014). "One can also speculate that women nonsmokers (the majority of EGFR positive patients), although having medical and breathing problems, are not considered being at risk of having lung cancer in spite of seeking medical attention relatively early." (PMID 24991207, 2014). "Lung cancer is not homogenous, and any change in histology or mutational status could happen after chemotherapy and/or targeted therapy, which suggests that EGFR wild-type should not be invalid indication for EGFR TKI." (PMID 25344762, 2014). "For example, EGFR-TKI resistance could be caused by MET amplification, HGF-triggered MET activation, Gas6-triggered AXL activation, and HER2 amplification in EGFR mutant lung cancer." (PMID 24952482, 2014). "While its significance is currently unknown, we note the nexus between EGFR inhibition and androgen activity, that anti-estrogens are used combined with Gefitinib against breast and lung cancers, whereas corticosteroids are used to treat side-effects of Gefitinib." (PMID 25184905, 2014). "EGFR (epidermal growth factor receptor) is a growth-factor-receptor tyrosine kinase which plays a vital role in proliferation, survival, migration, differentiation and metastasis of many tumors such as lung-cancer, head and neck cancer, breast cancer, gastric cancer, ovarian cancer." (PMID 24896265, 2014). "Thus, targeting EGFR can restore the tumor suppressive functions of GPRC5A in lung cancer." (PMID 25311788, 2014). "However, the specific role of mutated EGFR for aerobic glycolysis in lung cancer has not yet been clearly described." (PMID 24928511, 2014). "None of the ALK-positive lung carcinomas harbored coexisting EGFR mutations in the present study." (PMID 25295103, 2014). "Furthermore, mtDNA mutation content was significantly associated with epidermal growth factor receptor (EGFR) gene mutation (exons 19 and 21) in “never smokers” lung cancer patients." (PMID 24421769, 2013). "We used three lung cancer cell lines with T790M EGFR to test this hypothesis." (PMID 24189400, 2013). "Taken together, we suggest that CM1 could be developed as a therapeutic target of lung cancer regardless of EGFR mutation status." (PMID 23232551, 2013). "Also, miR-21 was shown to enhance the therapeutic effects of EGFR TKIs in lung cancer cell lines." (PMID 23802096, 2013). "The profile of EGFR phosphorylation in EGFR mutant lung cancer cells remains unclear." (PMID 23520446, 2013). "Indeed, a combination of an EGFR and Tankyrase inhibition recently revealed a close functional correlation of both pathways and confirmed the synergistic effect of a dual antagonistic treatment in lung cancer cells." (PMID 23016862, 2013). "The current knowledge with regard to GSK3β in lung cancer progression is based on the clinical observation that phosphorylated GSK3β (Ser 9, kinase dead) might be a good prognostic marker for the epidermal growth factor receptor (EGFR) overexpressing lung carcinoma." (PMID 24312384, 2013).
lung cancer (continued). "Indeed, MET and EGFR are both negatively correlated with survival in patients with lung cancer." (PMID 23844053, 2013). "However, several clinical indications suggest that EGFR-mutant lung cancers maintain partial sensitivity to TKIs despite development of acquired resistance and tumors can still be sensitive to EGFR-TKIs treatment beyond progression or re-treatment at further progression." (PMID 24167634, 2013). "Accumulating evidence has demonstrated that aberrant expression and activity of STAT3 is implicated in both carcinogenesis and development of drug resistance in several cancer types, including NSCLC, suggesting that STAT3 may contribute to resistance to EGFR TKI treatment in lung cancer." (PMID 24280348, 2013). "The epidermal growth factor receptor (EGFR) mutation status in the tyrosine kinase domain is known to be a predictor of the response to gefitinib or erlotinib in lung cancer; thus, a non-surgical procedure of tumor specimen collection is critical for mutation analysis." (PMID 23817662, 2013). "HGF may induce resistance to EGFR-TKIs in EGFR mutant lung cancer cells by Met/PI3K/Akt signaling." (PMID 23533466, 2013). "Blinded testing and analysis in a prospectively followed cohort of lung cancer patients treated with gefitinib alone demonstrated higher response rates and a marked increased in progression free survival for patients with a low Mig6/EGFR ratio (approximately 100 days, P = 0.01)." (PMID 23935914, 2013). "However, there is no report showing that bufalin could overcome HGF-induced EGFR-TKIs resistance in EGFR mutant lung cancer cells when combined with gefitinib or afatinib." (PMID 23533466, 2013). "A further study identified that cytohesins as EGFR activators may form a layer of positive regulation by facilitating the structural rearrangements required to convert the receptor dimer into its active conformation in lung cancer." (PMID 23420529, 2013). "In most lung cancer patients, EGFR is constitutively activated without evidence of mutation." (PMID 23866081, 2013). "Thus, the development of antibodies that specifically detect mutant EGFR protein by IHC could be a valuable addition to the current methods used to diagnose and predict response to treatment of lung cancer." (PMID 23419122, 2013). "In contrast, a recent study reported that different EGFR mutation testing methods, including PCR-Invader, peptide nucleic acid-locked nucleic acid (PNA-LNA) PCR clamp, direct sequencing, Cycleave, and ARMS, were carried out comparably in the analysis of FFPE and cytology lung carcinoma samples." (PMID 24364033, 2013). "Indeed EGFR was found to be overexpressed in several types of tumors including lung carcinomas." (PMID 23896512, 2013). "Moreover, dual inhibition of EGFR with an irreversible EGFR inhibitor (afatinib) and the EGFR neutralizing antibody cetuximab has recently shown promising activity in EGFR mutant lung cancers with acquired EGFR TKI resistance that harbor an EGFR T790M mutation." (PMID 22970367, 2012). "In addition to lung cancer, other tumors present low frequencies of EGFR mutations, like head and neck cancers, with no more than 7% of the patients carrying these alterations." (PMID 23207070, 2012). "We hypothesized that, similar to lung cancers of non-smokers, EGFR mutations might be more common in this etiological context than in ESCC occurring in the “Western” context of heavy combined tobacco and alcohol use." (PMID 23244191, 2012). "EGFR siRNAs or a similar technology that eliminates the receptor protein physically from the cancer cell could help to improve the treatment results in difficult to treat lung cancers." (PMID 22436374, 2012). "In addition, in a phase II nonrandomized study of the heat shock protein 90 (HSP-90) inhibitor, IPI-504, in patients with advanced lung cancer who previously progressed on EGFR TKI therapy, tumors from 3 patients were retrospectively found to have ALK rearrangements." (PMID 26316937, 2012).
lung cancer (continued). "Additionally, it is now well recognized that the epidermal growth factor receptor (EGFR) mutation positive lung cancers are more common in women and never-smokers." (PMID 24213497, 2012). "Alternatively, activation of the GRPR pathway may increase EGFR bronchial cell signaling in the absence of EGFR mutation, providing another route to lung cancer development in never smokers." (PMID 22296774, 2012). "Therefore, targeting of EGFR has achieved significant effects in the clinic; however, elevated EGFR activity is more frequent in never-smokers than smokers, so is less effective in smoking-related lung cancers." (PMID 22537942, 2012). "However, the polymorphism did not correlate with gender (p=0.5687), smoking (non-smokers vs. smokers, p=0.3325), or EGFR mutation (p=0.1539) statuses of lung cancer." (PMID 23226726, 2012). "In this regard, MUC1 and EGFR may serve as molecular targets for lung cancer prevention." (PMID 22457794, 2012). "EGFR mutations are specific to lung cancer and occur in mainly non-smokers." (PMID 22272264, 2012). "Mutations in EGFR have attracted attention because of their common occurrence in lung cancers of non-smokers (in particular in adenocarcinoma, women, and patients of Asian origin) and because of their significance as predictors of response to therapeutic tyrosine kinase inhibitors." (PMID 23244191, 2012). "And this newly established anti-cancer mechanism of curcumin might provide more clinical benefits especially in lung cancer, regardless of EGFR mutation status." (PMID 22489192, 2012). "Moreover, PIK3CA, the p110alpha catalytic subunit of PI3K, was found to be mutated in approximately 1.3% of Japanese lung cancer patient with EGFR mutations versus 2.1% in patients without EGFR mutations." (PMID 22970367, 2012). "Interestingly, the EGFR T790M mutation can also be found at low frequency (approximately 0.54% of never smokers with lung cancer) in the germ line of patients." (PMID 22970367, 2012). "The GRPR pathway is known to interact with the EGFR pathway in lung cancer cells by increasing the release of EGFR ligands such as amphiregulin, which could act to further promote cancer in never smokers who develop EGFR mutations." (PMID 22296774, 2012). "EGFR gene amplification, associated or not to EGFRvIII mutant expression, is frequently observed in other tumors like gliomas, lung cancers, breast, and prostate adenocarcinomas." (PMID 22623992, 2012). "In order to investigate whether TWIST1 could determine morphological changes in EGFR mutated tumors we analyzed the effect of TWIST1 expression in vitro and showed that in EGFR mutated lung cancer cells, EGF pathway stimulation and TWIST1 cooperated to induce an EMT and the associated cell mobility." (PMID 22272264, 2012). "For example, the overexpression and amplification of epidermal growth factor receptor (EGFR), and the underexpression and loss of dual specificity phosphate 4 (DUSP4), correlate strongly with each other; where each serves as an effective prognostic biomarker in lung cancer." (PMID 21935476, 2011). "Still, two other agents have been approved for the second-line treatment of lung cancer (NSCLC): erlotinib (Tarceva) and gefitinib (Iressa), which can produce a dramatic response in those subjects with activating mutations of the Epidermal Growth Factor Receptor (EGFR)." (PMID 21556173, 2011). "EML4-ALK, EGFR, and KRAS mutations were all mutually exclusive, suggesting that ALK mutation may be an important oncogenic factor, and a potential therapeutic target in EGFR wild-type and KRAS wild-type lung cancer." (PMID 21444946, 2011). "Similarly, our results implied that EGFR over-expression participated in lung cancer development." (PMID 21385353, 2011). "Unlike lung cancer and other tumors, EGFR gene mutations are uncommon in colorectal cancers." (PMID 21403829, 2011). "In addition, 20% of EGFR inhibitor refractory lung cancers have amplification of Met." (PMID 20624308, 2010).